TRPV4 (transient receptor potential cation channel subfamily V member 4)
Diseases named in the same sentence as TRPV4 in open-access papers (continued):
Sharing a sentence is not in itself a finding about the gene and the disease.
Cerebral ischemia (20 papers, 2012 to 2024). Restriction of arterial blood supply to the brain associated with insufficient oxygenation to support the metabolic requirements of the tissue. "Activation of TRPV4 is likely for its sensitivity to cell swelling, AA, and its metabolism EETs, which are always associated with cerebral ischemia." (PMID 23459987, 2013). "Therefore, it is likely that the apoptosis caused by TRPV4 activation likely contributes, at least in part, to the neuronal injury on the condition of cerebral ischemia." (PMID 26043075, 2015). "Transient receptor potential vanilloid 4 (TRPV4) is a calcium-permeable cation channel that is sensitive to cell swelling, arachidonic acid and its metabolites, epoxyeicosatrienoic acids, which are associated with cerebral ischemia." (PMID 26043075, 2015). "We conclude that blockage of TRPV4 may inhibit brain edema in cerebral ischemia through inhibiting MMP-9 activation and the loss of tight junction protein." (PMID 25914628, 2015). "Our data suggested that during cerebral ischemia, activation of TRPV4 may increase the activated MMP-9 level, leading to the loss of ZO-1 and occludin." (PMID 25914628, 2015). "Together with our early reports, the present data indicate that during cerebral ischemia, blockage of TRPV4 may inhibit the activation of MMP-9 and the loss of ZO-1 and occludin, which helps to reduce the disruption of BBB integrity and the subsequent vasogenic brain edema and brain injury." (PMID 25914628, 2015). "Matching, activation of TRPV4 channels has been reported in other neurological diseases like AD and cerebral ischemia leading to cell death, inflammatory cytokine release, and reactive oxygen species production." (PMID 38521959, 2024). "TRPV4 expression undergoes upregulation in the ipsilateral hippocampus following middle cerebral artery occlusion, contributing to neuronal injury during cerebral ischemia." (PMID 38256251, 2024). "In the following sections, we discuss the role of TRPV4 channels in specific cell types with the focus on their role in the cerebral ischemia." (PMID 37108263, 2023). "The activation of TRPV4 channels in neurons during cerebral ischemia enhances glutamate release and excitotoxicity, but it subsequently helps to replace the damaged neurons with new ones." (PMID 37108263, 2023). "In this review, we focus on one member of this family, the TRPV4, which is a particularly interesting Ca2+ permeable channel in terms of its contribution to the pathology of cerebral ischemia." (PMID 37108263, 2023). "The polymodal cation channel TRPV4, which mediates Ca2+ influx into the cell because of activation by various stimuli, is one of the potential therapeutic targets in the treatment of cerebral ischemia." (PMID 37108263, 2023). "This study demonstrated that Trpv4–/– mice showed reduced brain ischemia-induced lesion size and preserved BBB compared with WT mice in the acute phase." (PMID 32477057, 2020). "In recent studies, hyperactivation of TRPV4 resulted in neurotoxicity, which is involved in neuronal injury related to intracerebral hemorrhage, traumatic brain injury cerebral ischemia and infrasound-induced neuronal impairment." (PMID 31097691, 2019). "TRPV4 activation also aid in the destruction of blood-brain barrier and the subsequent brain edema in cerebral ischemia, traumatic brain injury and intracerebral hemorrhage." (PMID 31097691, 2019). "During cerebral ischemia, TRPV4 was over-activated by cytotoxic edema or the metabolites of arachidonic acid (AA), and TRPV4-mediated Ca2+ entry likely played a role in the intracellular Ca2+ overload." (PMID 29037241, 2017). "For example, TRPV4 protein levels are up-regulated during cerebral ischemia, and inhibition of TRPV4 reduces brain infarction." (PMID 27799895, 2016). "There is increasing evidence that TRPV4 is a promising target for the treatment of cerebral ischemia." (PMID 26043075, 2015).
Cerebral ischemia (continued). "The selectivity of HC-067047 makes it more promising and possible to explore the involvement of TRPV4 in cerebral ischemia." (PMID 23459987, 2013). "TRPV4 also plays a crucial role in neuronal damage during cerebral ischemia." (PMID 38256251, 2024). "When cerebral ischemia occurs, TRPV4 channels are activated and remain open, and Ca2+ enters cells through these TRPV4 channels, increasing the cell’s osmotic pressure and causing water to enter the cell through the water channel protein, ultimately leading to cell swelling and Ca2+ overload." (PMID 36982280, 2023). "Finally, it is also important to note that this channel is present in tissues of various body organs and therefore the potential side effects of TRPV4 channel modulation for the treatment of cerebral ischemia should be carefully evaluated." (PMID 37108263, 2023). "However, results from experiments modulating the TRPV4 function in animal models of cerebral ischemia are highly inconsistent." (PMID 37108263, 2023). "Therefore, it seems that the activation of TRPV4 channels during cerebral ischemia is detrimental for the mature neurons in the affected area, but it subsequently helps to replace the damaged neurons with new ones." (PMID 37108263, 2023). "In the pathology of cerebral ischemia, TRPV4 is involved in both harmful and protective processes." (PMID 37108263, 2023). "Additionally, the activation of TRPV4 is further enhanced by hyperthermia and can contribute to the development of a brain edema after cerebral ischemia, which again further enhances tissue damage." (PMID 37108263, 2023). "Both AQP4 and TRPV4 channels are involved in brain water and ion homeostasis, edema development, and cell volume regulation, and thus manipulation of their expression affects the impact of experimental cerebral ischemia." (PMID 36568889, 2022). "Therefore, we induced cerebral ischemia by tMCAO in Trpv4–/– and WT control mice and assessed their infarct sizes and neurological scores." (PMID 32974355, 2020). "Hyperactivation of TRPV4 occurs in pathological conditions (such as acute respiratory distress syndrome, cerebral ischemia and Alzheimer’s disease) and may result in cytotoxicity." (PMID 31097691, 2019). "Finally, TRPV4 blocking inhibits brain edema in cerebral ischemia, and reactive astrocytosis after stroke." (PMID 30255158, 2018). "Therefore, TRPV4 is likely a potential target for treating brain edema during cerebral ischemia and other pathological process." (PMID 25914628, 2015). "In summary, it is proposed that during the cerebral ischemia, the over-activation of TRPV4 results in caspase-3-dependent apoptosis through inhibiting PI3K/Akt and enhancing p38 MAPK signaling pathways, and this action contributes to cerebral ischemic neuronal injury." (PMID 26043075, 2015). "In fact, over-activation of TRPV4 may induce neuronal injury in cerebral ischemia through multiple mechanisms." (PMID 23459987, 2013). "Closing TRPV4 may exert potent neuroprotection against cerebral ischemia injury through many mechanisms at least including the prevention of NMDAR-mediated glutamate excitotoxicity." (PMID 23459987, 2013). "As glutamate excitotoxicity is of great importance in cerebral ischemia injury, we firstly explored whether TRPV4 activation modulated NMDAR function." (PMID 23459987, 2013). "Moreover, this is the first study describing the impact of global cerebral ischemia in vivo on TRPV4-mediated currents and intracellular Ca2+ signaling in hippocampal astrocytes." (PMID 22761937, 2012). "Therefore, TRPV4 is often highlighted as a potential target for the treatment of cerebral ischemia." (PMID 37108263, 2023). "Thus, changes in TRPV4 expression and its activity as possible treatments for cerebral ischemia remain unclear." (PMID 36568889, 2022). "However, it remains unclear whether TRPV4 is activated via temperature-dependent mechanisms in the process of brain ischemia." (PMID 35008663, 2021).
Cerebral ischemia (continued). "Therefore, it is proposed that TRPV4-mediated enhancement of oxidative stress is likely responsible for the neuronal injury in cerebral ischemia injury; however, this hypothesis should be further confirmed." (PMID 27799895, 2016). "We herein present a study of the effect of TRPV4 and AQP4 channel deletion on astrocyte swelling and their ability to regulate cell volume under conditions modeling cerebral ischemia." (PMID 38818517, 2024). "But for the lack of selectivity of these blockers, the role of TRPV4 in cerebral ischemia injury remains to be determined." (PMID 23459987, 2013). "The potential contribution of these channels to the regulation of arterial tone via endothelial TRPV4 cannot be ruled out, as they are critical for endothelial-mediated dilation, known to be impaired by brain ischemia, and are contributors to angiogenesis and neovascularization." (PMID 33410092, 2021).
atherosclerosis (19 papers, 2016 to 2025). A disease characterized by the build-up of fatty material and calcium deposition in the arterial wall resulting in partial or complete occlusion of the arterial lumen. "Matrix stiffening is a hallmark of atherosclerosis and other fibrotic diseases, and the role of TRPV4 as a stiffness sensor positions it as a critical mediator of pathological remodeling in these conditions." (PMID 41388869, 2025). "While TRPV4 has been implicated in macrophage foam cell formation in atherosclerosis, its role in EC inflammation remains understudied." (PMID 41309549, 2025). "We show that in atherosclerosis, a chronic inflammatory condition associated with matrix stiffening, TRPV4 decreases miR-146a expression in aortic tissue macrophages." (PMID 39403372, 2024). "Transient receptor potential vanilloid channel member 4 (TRPV4) has been implicated in the formation of macrophage-derived foam cells and the development of atherosclerosis." (PMID 37588590, 2023). "Our current data appear to have identified a specific plasma membrane receptor/channel, TRPV4, as a potential mediator of inflammatory/proatherogenic responses associated with pathogenesis of periodontitis‐induced atherosclerosis." (PMID 30980509, 2019). "These in vivo results demonstrate that TRPV4 hyperactivation exacerbates atherosclerosis by promoting inflammation and NLRP3 activation, whereas its inhibition confers strong protection, establishing TRPV4 as a key mechanistic target for treatment." (PMID 41309549, 2025). "Our study investigates how transient receptor potential vanilloid 4 (TRPV4), a mechanosensitive ion channel, interacts with microRNA-146a (miR-146a), within the context of inflammation and atherosclerosis." (PMID 39403372, 2024). "TRPV4 has a complex role in atherosclerosis, involving foam cell formation, endothelial dysfunction, and inflammation." (PMID 39334952, 2024). "We show that in atherosclerosis, a condition characterized by matrix stiffening, TRPV4 decreases miR-146a expression in aortic tissue macrophages." (PMID 39403372, 2024). "In a study using human monocytes, inhibition of TRPV4 reduces monocyte/macrophage adhesion to endothelial cells to regulate the progression of atherosclerosis." (PMID 37588590, 2023). "Overall, TRPV4 likely plays a complex and multifaceted role in atherosclerosis development and agonism or antagonism with pharmaceutical intervention requires additional study before translation for human therapy." (PMID 34914760, 2021). "TRPV4 is a calcium channel and plays a protective role during atherosclerosis by regulating monocyte recruitment to the forming plaque." (PMID 34914760, 2021). "Considered all together, these findings suggest TRPV4 as an attractive target in atherosclerosis and other diseases, thus incentivizing the discovery of small molecule inhibitors of TRPV4 that can be translated into clinically effective therapeutics." (PMID 33854174, 2021). "Finally, in vivo studies are needed to validate the therapeutic potential of TRPV4 inhibition in mitigating vascular stiffening and atherosclerosis." (PMID 41388869, 2025). "In addition, genes related to the TGFβ pathway, such as BMP2 and TRPV4, the Wnt pathway, and the cell senescence signaling pathway can be targeted in arteries to prevent vascular calcification or atherosclerosis under diabetic or uremic conditions." (PMID 41465376, 2025). "Furthermore, we show that miR-146a levels decrease in macrophages exposed to high matrix stiffness, as well as in aortic tissues in atherosclerosis- a condition characterized by matrix stiffening- and this decrease is driven by TRPV4." (PMID 39403372, 2024). "Despite these findings, effective TRPV4 inhibitors for atherosclerosis must be further explored." (PMID 39334952, 2024). "In addition to its direct effects on macrophages, TRPV4 contributes to atherosclerosis by regulating endothelial cell function." (PMID 37588590, 2023).
atherosclerosis (continued). "Activation of TRPV4 inhibits monocyte adhesion and atherosclerosis." (PMID 37588590, 2023). "Therefore, the relationship between Piezo1 and TRPV4 in the endothelium and initiation and perpetuation of atherosclerosis is more complicated than what can be studied in vitro." (PMID 33298523, 2021). "It has been proposed that activation of TRPV4 can limit vascular inflammation and atherosclerosis." (PMID 32481620, 2020). "This prompted several other research groups to broaden the study of the functions of TRPV4 in endothelial cells since it could be of importance for diseases such as hypertension, atherosclerosis, diabetic vasculopathy, vascular tumors, stroke, etc." (PMID 32481620, 2020). "In summary, the present study demonstrates that GSK1016790A, a specific and potent small-molecule activator of mechanosensitive ion channel TRPV4, induces eNOS phosphorylation and activation, and inhibits leukocyte adhesion to endothelium and the eventual development of atherosclerosis in mice." (PMID 27191895, 2016). "Together, the present study suggests that pharmacological activation of TRPV4 may serve as a potential therapeutic approach to treat atherosclerosis." (PMID 27191895, 2016). "Notably, TRPV4-mediated mechanical sensing intersects with the AFM-observed biomechanical changes: TRPV4 upregulation in atherosclerosis likely exacerbates membrane tension and disrupts EC mechanical properties (height, area, elastic modulus), whereas TRPV4 downregulation restores these parameters." (PMID 41309549, 2025). "It remains unknown regarding the precise role of TRPV4 in mouse and human atherosclerosis and whether endothelial function and atherosclerosis development will be exaggerated in TRPV4−/−; ApoE−/− mice, or in ApoE−/− mice treated with the TRPV4 inhibitor GSK2193874." (PMID 27191895, 2016). "Therefore, targeting TRPV4 might be a potential therapeutic tactic to treat atherosclerosis." (PMID 33981725, 2021). "This process raises the possibility that the interaction of TRPV4 with adherens junction proteins and force-dependent Ca2+ influx may play a regulatory function in the mechanotransduction of blood flow and the development of atherosclerosis in regions where blood flow is disturbed." (PMID 30728775, 2019). "In addition, GSTA4, RAPGEF3, TRPV4, INSIG1, UTS2, and PPP1R1A all play a role in the development of atherosclerosis." (PMID 39758846, 2024). "However, it remains unknown whether pharmacological activation of TRPV4 by GSK1016790A can elicits laminar flow signaling events and prevents the development of atherosclerosis." (PMID 27191895, 2016). "Here, we sought to explore whether non-mechanical activation of TRPV4 could limit vascular inflammation and atherosclerosis." (PMID 27191895, 2016).
melanoma (19 papers, 2018 to 2025). A malignant, usually aggressive tumor composed of atypical, neoplastic melanocytes. "TRPM1 is implicated as a tumor suppressor, whereas TRPM7, TRPV1, and TRPV4 often function as both melanoma suppressor or oncogenic drivers, modulating proliferation, apoptosis, and metastasis." (PMID 40869148, 2025). "TRPM1 has been implicated in tumor suppression, while TRPM7, TRPV1, and TRPV4 have been observed to function as both melanoma suppressors and oncogenic drivers, modulating proliferation, apoptosis and metastasis." (PMID 40869148, 2025). "TRPV1 and TRPV4, members of the vanilloid subfamily, have been implicated in melanoma biology, though their roles remain somewhat controversial." (PMID 40869148, 2025). "An early study showed that Src kinases phosphorylate TRPV4 during hypotonic stress and, recently, TRPV4 was associated with the migration of endometrial cancer or melanoma cells." (PMID 37507867, 2023). "Our study revealed a signaling mechanism underlying stimulus-triggered exocytosis in melanoma and highlighted the role of cellular sensor TRPV4 ion channel in mediating ferroptosis." (PMID 35456964, 2022). "Pharmacological TRPV4 activation in human melanoma cells and keratinocytes caused severe cellular disarrangement, necrosis and apoptosis." (PMID 29293584, 2018). "Since AKT and MAPK signaling pathways are commonly associated with cell apoptosis, we hypothesized that TRPV4 may mediate cell apoptosis of melanoma via AKT or MAPK signaling pathway." (PMID 30881453, 2019). "In the following, we show that human melanoma cell lines expressed functional TRPV4 channels and that the TRPV4-activator, GSK1016790A, caused a strong calcium-overload and cellular disarrangement, increased the rate of apoptosis, and strongly inhibited cell proliferation/survival." (PMID 29293584, 2018). "Indeed, in vivo TRPV4 deficiency inhibited the invasion and migration of melanoma cells." (PMID 36499486, 2022). "Altered expression patterns and functional changes in TRPM1, TRPM7, TRPM8, TRPV1, and TRPV4 have notably been found to modulate cell survival, apoptosis, proliferation, and migration in melanoma models." (PMID 40869148, 2025). "The authors showed that TRPV4 stimulation in melanoma cell lines changed mitochondria structure and crista morphology." (PMID 37507867, 2023). "TRPV4 induced melanoma metastasis by Src-cofilin intracellular pathway but, unexpectedly, this study showed that TRPV4 activates the phosphorylation of Src kinase." (PMID 37507867, 2023). "As reported for redox TRP channels, recent studies showed that stimulation of TRPV4 induces exocytosis and leads to ferroptosis of human melanoma cell." (PMID 37507867, 2023). "Fura-2 imaging of Ca2+ activity showed that GSK1016790A produced rapid and sustained intracellular Ca2+ elevation in melanoma cells, and the level of intracellular Ca2+ elevation was positively correlated with the expression of TRPV4." (PMID 36499486, 2022). "However, the underlying mechanism in conjunction with TRPV4 and melanoma remains unknown." (PMID 36499486, 2022). "So far, our data reveal that the expression levels for clathrin, vimentin, and SNX9 increased during TRPV4 activation induced exocytosis in human melanoma A375 cells." (PMID 35456964, 2022). "We previously found that TRPV4 ion channel is over-expressed in human melanoma A375 cells, and that activation of TRPV4 induced cell death." (PMID 35456964, 2022). "In summary, activation of endogenous TRPV4 in human melanoma A375 cells triggered prominent and progressive exocytosis, which likely led to eventual cell death." (PMID 35456964, 2022). "Collectively, targeting TRPV4 is now a promising area of cancer therapy, and Baicalin is a potential therapeutic drug targeting TRPV4 for the prevention and therapy of melanoma metastasis." (PMID 36499486, 2022).